CCR7 (C-C motif chemokine receptor 7)
Diseases named in the same sentence as CCR7 in open-access papers (continued):
Sharing a sentence is not in itself a finding about the gene and the disease.
Sepsis (continued). "We observed the identical trend regarding the protein expression of mregDC marker genes, including CCR7, CD274 (PD-L1), and CD80, which were consistently upregulated and enriched at 24 h after sepsis." (PMID 35832091, 2022). "Therefore, we speculate that CCR7 has a critical role in the diagnosis and treatment of sepsis." (PMID 36457745, 2022). "In addition, we identified key genes that were upregulated in sepsis, namely, S100A8, S100A9, and CR1, as well as those that were downregulated, namely, CD79A, HLA-DQB2, PLD4, and CCR7." (PMID 37298316, 2023). "CXCR3, CCR7, HLA-DMA, and GPR18 might be correlated with the sepsis mechanism." (PMID 34484417, 2021). "CXCR3, CCR7, HLA-DMA, and GPR18 might participate in the mechanism of CAP with sepsis." (PMID 34484417, 2021). "However, the expression level and positive-cell ratio of CCR2 and CCR7 among CD3ε-B220-Gr-1-TER119-CD11c+MHC class II+ cells did not exhibit any sepsis-induced remarkable alteration." (PMID 31323786, 2019).
colon carcinoma (17 papers, 2007 to 2025). "Noteworthy examples include the overexpression of CXCR2 in NK cells targeting renal cell carcinoma and the combined overexpression of CXCR4 and CCR7 for colon cancer." (PMID 39339180, 2024). "In an in vitro/in vivo mouse experiment, CCR7 in SW620 human colon carcinoma cells was knocked down in cell culture using anti-CCR7 siRNA." (PMID 35203305, 2022). "The transmembrane protein CCR7 is correlated with the spread of cancer to the lymph nodes in colon cancer and thus considered a beneficial therapeutic target." (PMID 35874608, 2022). "Specifically, MMP-9 is expressed in CCR7-expressing colon cancers, with a downstream response of lymph node metastasis." (PMID 35203305, 2022). "It has been found that inhibition of CCR7 can effectively reduce the number of tumor metastases in colon cancer models." (PMID 36589748, 2022). "For the first time, we demonstrated that macrophages under the influence of colon cancer cells and hypoxia significantly decreased CCR7 expression, in line with other reports of macrophages monocultures." (PMID 32231135, 2020). "In colon cancer, a study suggests that CCR7 promotes metastasis by upregulating matrix metalloproteinase-9 (MMP-9) expression." (PMID 24259307, 2013). "According to one study, CCL21/CCR7 played an important role in human colon cancer metastasis." (PMID 36829431, 2023). "CCR7 expression plays a key role in the ability of tumor cells to invade and metastasize in SW620 human colon cancer cell mice xenografted model." (PMID 33158173, 2020). "In contrast to the ERK1/2 phosphorylation response to CCR7/CCL19 activation observed in immune cells, the colon cancer cells did not appear to express functional CCR7, since the cells failed to activate signaling pathways via CCL19 or CCL21 to ERK1/2." (PMID 35203305, 2022). "However, whilst SW480 (human colon cancer) cells do express CXCR4, their expression of CCR7 is negligible." (PMID 28432337, 2017). "By contrast, conditioned medium of EGFR knockout colon cancer cells inhibited expression of these M2-related markers and induced macrophage expression of the M1-related markers inducible nitric oxide synthase (iNOS), IL-12, TNF-α and CCR7." (PMID 27683110, 2016). "Thus, the function of CXCR3 in colon cancer may depend on its cooperation with other expressed chemokine receptors such as CXCR4 and CCR7." (PMID 24259307, 2013).
influenza (17 papers, 2009 to 2024). An acute viral infection of the respiratory tract, occurring in isolated cases, in epidemics, or in pandemics; it is caused by serologically different strains of viruses (influenzaviruses) designated A, B, and C, has a 3-day incubation period, and usually lasts for 3 to 10 days. "After influenza infection, the relative numbers of CCR7 expressing mDCs increased in both groups to a similar extent." (PMID 23326231, 2013). "Our results also indicated that the percentage of mDCs that express CCR7 was low under steady state in the C3−/− mice and remained low during influenza infection despite CCR7 upregulation." (PMID 23326231, 2013). "Furthermore, when we collectively examined the CCR7 expression on samples from D7 post-first vaccination from both vaccine groups, we found similar results as those for the influenza samples in S2C Fig." (PMID 26333070, 2015). "CCR7−/− mice exhibit a normal component of lung-residing CD103+ and CD11bhi RDC (and not depicted) but these two DC subsets (unlike Gr-1+ MoDC) failed to accumulate in the MLN of influenza-infected CCR7-deficient mice." (PMID 19145246, 2009). "Published transcriptional profiles of NK cells, ILC1, and influenza-specific Id2-deficient mouse CD8+ T cells showed a striking concordance of Id2-dependent expression with our innateness gradient genes, highlighted by TBX21, ZEB2, IL18RAP, CCR7, TCF7, cytotoxicity, and KLR genes." (PMID 30737409, 2019). "As expected with CMV-based vectors, CyCMV/Flu-elicited CD4+ and CD8 + T cells recognizing influenza antigens exhibited a predominantly TEM phenotype in peripheral blood as measured by expression of CD28 and CCR7." (PMID 39030218, 2024). "Based on reported alterations in T cell memory phenotype associated with aging and impaired antibody responses to the influenza vaccine, CD8+ naive cells (CD45RA+ CCR7+) and CD8 + CD28- TEMRA cells (CD45RA+ CCR7- CD28-) were selected for assessment." (PMID 36650551, 2023). "Within this T cell population, frequencies of CD95+ late effector (CD45RA+CCR7-) and naive (CD45RA+CCR7+) CD8+ memory T cells correlated inversely with self-reported influenza illness (ILI) symptoms." (PMID 29145441, 2017). "In the absence of significant changes in other NK cell markers (CD45RO, NKp44, CXCR6, CD57, NKG2C, CCR7, CD62L and CD27), influenza vaccines induced memory NK cells with the distinct feature of intracellular NKp46 expression." (PMID 25781472, 2015). "The stimulation/recall of antigen-specific memory CD4+ T cells, derived from previous influenza infections or vaccinations, was assessed by the frequencies of cytokine-secreting central memory (CM) and effector memory (EM) T cell populations (CD45RA- CCR7+ and CD45RA- CCR7-, respectively)." (PMID 36371426, 2022). "Phenotypic ex vivo analyses of immunodominant and subdominant influenza-specific A2/M158+CD8+ T cells involved CCR7 and CD45RA expression to characterize naïve (TN, CCR7+CD45RA+), central memory (TCM, CCR7+CD45RA-), effector memory (TEM, CCR7-CD45RA-) and effector (TEFF, CCR7-CD45RA+) T cells." (PMID 32750095, 2020). "Compared with the placebo-injected group, vaccination with the influenza vaccines did not result in remarkable changes in the percentage of CD39+ or CCR7+ aTreg." (PMID 28658271, 2017). "Extensive surface phenotyping was performed together with combinatorial tetramer staining to measure the frequency, memory status (CD45RA and CCR7), chemokine receptor expression (CXCR3, CCR4, CCR6 and CXCR5) as well as activation status (CD38) of these influenza-specific T cells." (PMID 27571776, 2016). "Interestingly, we observed that seasonal influenza vaccination elicited median increases in PD-1 MFI on both CCR7- and CCR7+ subsets, specifically in CXCR3+CCR6- cTFH, and the magnitude of increase was greater within the CCR7- subset." (PMID 30303980, 2018).
influenza (continued). "In this study, we have described in detail for the first time porcine influenza-specific CD8 T cells in lymphoid and non-lymphoid tissues and shown that antibodies to CD45RA and CCR7 identify four subsets: naïve, TCM, TEM and TDE." (PMID 35145208, 2022).
breast tumor (16 papers, 2013 to 2025). "In this study, we extend our work to investigate the expression and association of TAK1 and CCR7 in breast tumor tissues." (PMID 25557171, 2015). "However, the expression and association of activated TAK1 and CCR7 in breast tumor tissues is unknown and the therapeutic effect by targeting TAK1 is also unclear." (PMID 25557171, 2015). "For example, CCR7 and CD40 upregulation has also been linked to cDC1 and cDC2 states in human breast tumors." (PMID 40953263, 2025). "Kaplan–Meier survival plots indicated that CCR7- and EGFR-expressing breast tumors were associated with a shorter survival time compared to patients expressing low levels of the receptors." (PMID 35203305, 2022). "Mechanistically, VEGF-C elevated CCL21 lymphatic secretion, resulting in the chemotactic migration of CCR7-expressing breast tumor cells towards lymphatic vessels, promoting proliferation, migration and tube formation of primary lymphatic endothelial cells." (PMID 35203305, 2022). "The expression level of CCR7 in breast tumors can be low and in one study, CCR7 was present in only 10% of patients." (PMID 35203305, 2022). "The role of the CCL21/CCR7 axis in the breast tumor microenvironment was further analysed for the tumor cell interaction with stromal cells, namely the cancer associated fibroblasts." (PMID 28416768, 2017). "Therefore, Ifng activates the Ccl19/Ccl21/Ccr7 axis between breast tumors and SRC-3 KO Tregs to signal the recruitment of SRC-3 KO Tregs into breast tumors." (PMID 37253006, 2023). "Furthermore the effect of CCR7 on tumor progression in primary mouse and human breast tumors is mediated through stem-like cells by decreasing their ability to self-renew and triggering neoplasia." (PMID 28416768, 2017). "CCR7, EZR, IDH2 and MMP9 were highly expressed in breast tumor tissues, whereas they were expressed at low levels in normal breast tissues (p < 0.001)." (PMID 38438469, 2024). "The majority of the CD4+ T cells in all breast tumors are TEM (CD45RA−CCR7−; 88%), followed by a small group of TEMRA (CD45RA+CCR7−; 8%), TCM (CD45RA−CCR7+;4%), and TNAIVE (CD45RA+CCR7+; 1%)." (PMID 33467084, 2021). "More recent data indicated that in addition to CXCR4 and CCR7 and its ligands also EGFR was significantly higher expressed in breast tumor cells with lymph node metastasis, which was correlated to shorter survival period of afflicted patients." (PMID 23667660, 2013). "Of note, analysis of a publicly available gene expression database demonstrated that it is not the high individual expression of CXCR4 and CCR7, but their enhanced co-expression levels that significantly correlate with the increase in breast tumour grade." (PMID 34685420, 2021). "The majority of CD8+ T cells in all breast tumor subtypes are TEM (CD45RA−CCR7−; 72%), accompanied by a smaller group of TEMRA (effector memory CD45RA+, CD45RA+ CCR7−; 23%), and minor populations of TCM (central memory, CD45RA−CCR7+; 3%), and TNAIVE (CD45RA+CCR7+;1%)." (PMID 33467084, 2021). "De novo expression of CCR7 is sufficient to induce preferential metastasis to the lymph nodes in several human and mouse breast tumor cell lines that, without CCR7 expression, normally metastasize solely to the lung." (PMID 24259307, 2013). "High levels of CCR7 are consistently expressed in breast tumor cells along with CXCR4, though CCR7 is also expressed in normal mammary epithelial cells." (PMID 24259307, 2013). "The results showed that CCL5 and IDH2 were not significantly differentially methylated in BRCA, while CCR7, EZR, IL8, and IL2RG were hypermethylated in normal tissues, and FLT3, MAPK10, and MMP9 were hypermethylated in breast tumor tissues." (PMID 38438469, 2024).
HIV-1 infection (16 papers, 2007 to 2025). The type species of lentivirus and the etiologic agent of acquired immunodeficiency syndrome (AIDS). "The CCR7 expression pattern is strongly correlated with increased HIV-1 viral reservoirs and is associated with chronic HIV-1 infection." (PMID 31632965, 2019). "We report a substantial relative and absolute increase of CCR7−CD56bright NK cells and conversely diminished numbers of CCR7+CD56bright NK cells in viremic HIV-1 infection." (PMID 23028633, 2012). "The finding that CD69-expression is substantially increased on the CCR7-CD56bright population supports a dominant role for immune activation in the observed alteration of this NK cell phenotype in chronic HIV-1 infection." (PMID 23028633, 2012). "It has been reported that Tim-3-expressing CD8+ T cells during HCV or HIV-1 infection display either dominant CCR7+ central memory or CCR7+ and/or CD27+ phenotype profiles with no or low expression of effector surrogate marker CD127." (PMID 23144609, 2012). "In this vein, a recent report described the emergence of an unusual CD4+ CD45RA+ CCR7− CCR5+ memory population in infected people that is resistant to HIV-1 infection." (PMID 18941536, 2008). "Future studies may test whether HIV-1 infection can block T-cell-progenitor seeding to the thymus by downregulating CCR7 expression on CLPs." (PMID 31165736, 2019). "In summary, we showed that untreated HIV-1 infection is characterized by elevated expression of CCR7 and CD62L on plasmacytoid dendritic cells, which relocate to lymph nodes, acquire an activated but immature phenotype, and express elevated amounts of IFNα before undergoing cell death." (PMID 20559432, 2010). "Using these two parameters, a differentiation block from effector memory cells (CCR7−/CCD45RA−) to terminally differentiated effector cells (CCR7−/CD45RA+) has been reported in chronic progressive HIV-1 infection, resulting in a relative paucity of fully mature virus-specific effector CD8+ T cells." (PMID 17389912, 2007). "In HIV-1 infection, CD4+T cells exhibited a skewed maturation from naive (CD45RA+CCR7+) and central memory (CD45RA−CCR7+) toward the effector memory (CD45RA–CCR7–) compartment." (PMID 38267841, 2024). "We used CD3+CD4+CD45RO+CCR7+ central memory T cells (CMT) for HIV-1 infection and culture in the presence of CCL19 to establish HIV latent infection." (PMID 32792548, 2020). "The increased levels of the three phospho-proteins during HIV-1 infection were observed across all memory subsets that are determined by differential expression of CD27 and CCR7 markers." (PMID 31658294, 2019). "During HIV-1 infection, the CCL19/CCR7 axis assists with establishing a latent infection." (PMID 31632965, 2019). "The proportion of CCR7+ NK cells was decreased with later category of primary HIV-1 infection but did not return to baseline (p<0.0001)." (PMID 23326405, 2013). "Based on the linear differentiation model of CD8+ T cells defined by the lineage markers CD45RA and CCR7, it has been proposed that chronic progressive HIV-1 infection is related to a maturation block from effector memory phenotype (EM, CD45RA−/CCR7−) to full effector phenotype (E, CD45RA+/CCR7−)." (PMID 17389912, 2007). "To investigate whether GPR15 expression on these T cell subsets is altered in the context of HIV-1 infection, we analyzed surface expression of GPR15 on CCR7+CD45RA− central memory, CCR7−CD45RA− effector memory and CCR7+CD45RA+ naïve CD4+ T cells from healthy donors and HIV-1 infected individuals." (PMID 24558379, 2014). "While naïve T cells with or without HIV-1 infection retained their CD45RO–CCR7+ surface phenotypes, CMT (CD45RO+CCR7+) and EMT (CD45RO+CCR7–) showed some decreases in CCR7 expression after culture." (PMID 36742330, 2023).
multiple sclerosis (16 papers, 2009 to 2026). A progressive autoimmune disorder affecting the central nervous system resulting in demyelination. "The regulation of Tfh cell differentiation by CCR7 significantly impacts multiple sclerosis relapse." (PMID 38361743, 2024). "A non-selective S1P receptor modulator, called fingolimod, which disrupts lymphocyte trafficking by trapping the CCR7+ T cells in LNs is already used as a therapeutic agent in multiple sclerosis." (PMID 35163775, 2022). "CCR7 has been shown to drive cancer and to be involved in multiple sclerosis progression and development of graft-versus-host disease thus playing a dual role in health and disease." (PMID 28018341, 2016). "CCR7 significantly affects multiple sclerosis relapse by regulating Tfh cell differentiation." (PMID 36312035, 2022). "CCR7 activity has been implicated in the neuroinflammatory and autoimmune processes of diseases such as multiple sclerosis, but has not yet been directly implicated in AD." (PMID 32155778, 2020). "Research on multiple sclerosis indicates that cerebrospinal fluid levels of CCL19 correlate with the numbers of T cells and CCR7 + dendritic cells." (PMID 41481752, 2026).
B-cell chronic lymphocytic leukemia (15 papers, 2010 to 2025). "Furthermore, inheritance of the CCR7 rs3136685 AG+AA or CCR7 rs3136687 (AG, AG+AA) genotypes was associated with a 60-62% reduction in multiple myeloma (MM) and chronic lymphocytic leukemia, respectively." (PMID 23168091, 2012). "CAP-100 (NCT04704323) and JBH492 (NCT04240704), monoclonal antibodies against CCR7, have been involved in Phase I clinical trials for Chronic lymphocytic leukemia and Non-Hodgkin lymphoma." (PMID 40455785, 2025). "On the other side, some studies indicated that CCR7/CCL21 interaction regulates MMP9 gene transcription by regulating Extracellular signal-related kinase (ERK)-effector c-Fos (AP1 complex) in B-cell chronic lymphocytic leukemia cell." (PMID 30781353, 2019). "In addition, CCR7 is recognized as a therapeutic target in hematologic malignancies, such as T-cell prolymphocytic leukemia, B-cell chronic lymphocytic leukemia, and non-Hodgkin's lymphoma." (PMID 40028039, 2025). "CCR7/CCL21 can promote the invasion and metastasis ability of B-cell chronic lymphocytic leukemia cells by activating phosphoinositide-3 kinase and the Rho effector molecule Rho-associated coiled-coil forming protein kinases (ROCK)." (PMID 33158173, 2020). "Moreover, the first humanized anti-CCR7 antibody was approved for the treatment of patients with relapsed/refractory chronic lymphocytic leukemia (NCT04704323), highlighting CCR7’s potential as a key target in cancer therapy." (PMID 40299690, 2025).